ZEB2 (zinc finger E-box binding homeobox 2)
Diseases named in the same sentence as ZEB2 in open-access papers (continued):
Sharing a sentence is not in itself a finding about the gene and the disease.
breast carcinoma (continued). "Fukagawa and collaborators showed in a panel of breast cancer cell lines that CDH1 has different levels of methylation that correlate with ZEB1 and ZEB2 expression levels." (PMID 30445998, 2018). "To verify that FOXP3 regulates the endogenous ZEB2 gene, we examined the effect of enforced FOXP3 expression in BT549 breast cancer cells, which normally have low levels of FOXP3 and express ZEB2." (PMID 29963231, 2018). "It has been shown that miR-103/107 induces EMT in breast cancer by downregulating miR-200, which targets the E-cadherin negative regulators ZEB1 and ZEB2." (PMID 28974015, 2017). "Researches have shown that ZEB2, TGFB1, MDM2 are important downstream effectors that can be inhibited by GATA3 in breast cancer." (PMID 28599307, 2017). "Downregulation of E-cadherin is one of the critical markers of EMT in human breast cancers, and FOXC2, Twist, ZEB1, ZEB2, Slug, and Snail are transcription factors that repress E-cadherin transcription." (PMID 28212558, 2017). "This study helps to delineate a complex signaling network in breast cancer mediated by miR-29b and presents a miR-29b/TET1/ZEB2 pathway involved in the progression of breast cancer." (PMID 29254230, 2017). "The targets of the top luminal miRNAs were activators of EMT (ZEB1, ZEB2) and basal subtype transcription (IL-6, EGFR, STAT3), whereas the targets of the top basal miRNAs were involved in adipogenesis pathways and luminal breast cancer (ERBB2, ERBB3)." (PMID 27845906, 2016). "miR-200b over-expression inhibited the transcriptional repressor ZEB2 and CDH1 in breast carcinoma cells." (PMID 27081085, 2016). "In this study, we found that δEF1 bound to DNMT1 in breast cancer cells of the basal-like subtype, and that silencing of δEF1 family proteins (δEF1/ZEB1 and SIP1/ZEB2) considerably decreased the number of 5mC sites." (PMID 25315069, 2015). "Up-regulation of Snail and Zeb2, along with repressed expression of Sfrp1, are features of EMT which contribute to mammary tumours." (PMID 23883065, 2013). "The focus of this study was underpinned by the common reactivation of ZEB1, ZEB2 and TWIST1 in aggressive and undifferentiated human breast cancers, especially in the newly identified claudin-low intrinsic subtype." (PMID 22654675, 2012). "It is thought that the mechanism by which ZEB2 induces EMT is by its ability to repress the epithelial cell junction protein E-cadherin and induce the mesenchymal marker, vimentin, in breast cancer cell lines." (PMID 21303533, 2011). "A recent study showed that the expression of miR-200b, which targets both ZEB1 and ZEB2, was downregulated in the cells that undergo TGF-beta-induced epithelial to mesenchymal transition (EMT), and was lost in invasive breast cancer cells." (PMID 21682903, 2011). "EMT transcription factors such as SNAIL and ZEB2 can inhibit cell cycle transition by inhibiting the transcription of CCND2 and CCND1, respectively, ZEB1 protein degradation induced by CDK4/6 inhibition blocks breast cancer metastasis." (PMID 39949984, 2025). "In breast cancer, for example, the delivery of miR-200c-3p using tumor-targeted nanoparticles has shown promise in inhibiting tumor growth and metastasis by downregulating oncogenes like ZEB1 and ZEB2." (PMID 39859424, 2025). "Previous studies have indicated that ZEB2 induces EMT by inhibiting the expression of E-cadherin, promotes cell migration and invasion, and plays a pro-cancer role in many types of cancer, such as breast cancer, hepatocellular carcinoma and NSCLC." (PMID 38610009, 2024). "Together, these results indicated that CLDN4 is a direct GRHL2 target while CDH1, ZEB1, or ZEB2 are unlikely to represent direct GRHL2 target genes in luminal breast cancer cells." (PMID 36691073, 2023).
breast carcinoma (continued). "In the present study, we demonstrate a novel positive feedback loop between the EMT transcription factor ZEB2 and the essential lipid metabolic enzyme ACSL4, resulting in enhanced cellular LDs accumulation and fatty acid oxidation (FAO) to drive breast cancer metastasis." (PMID 38078907, 2023). "The expression and relationship of ZEB2 and ACSL4 in breast cancer." (PMID 38078907, 2023). "Notably, EMT and stemness genes such as ZEB2, SNAIL, TWIST, Gli2, WNT, and AKT3, which are overexpressed in basal-like breast cancer (BLBC), were significantly upregulated in drug-resistant cells." (PMID 38078907, 2023). "We do not detect GRHL2 binding sites in ZEB1 or ZEB2, across all the luminal and basal A breast cancer cell lines we have analyzed, which contrasts with previous findings in other cell types." (PMID 36768838, 2023). "Furthermore, using METABRIC data, we found positive correlations between expression of ZFP36 and genes associated with the stem-like phenotype, as TWIST1, TWIST2, SNAI1, ZEB1, ZEB2, ALDH1A and YAP1 in all breast cancer subtypes." (PMID 38274271, 2023). "In conclusion, we provide insights into the mechanistic links between EMT and lipid metabolism and identify the ZEB2/ACSL4 axis as a novel metastatic metabolic pathway that stimulates both lipogenesis and FAO, resulting in enhanced breast cancer invasion and metastasis." (PMID 38078907, 2023). "In conclusion, we reveal a novel positive regulatory loop between ZEB2 and ACSL4, which promotes LDs storage to meet the energy needs of breast cancer metastasis, and identify the ZEB2–ACSL4 signaling axis as an attractive therapeutic target for overcoming breast cancer metastasis." (PMID 38078907, 2023). "Importantly, we observed a strong correlation between ZEB2 and ACSL4 expression levels in clinical breast cancer samples." (PMID 38078907, 2023). "CRL4B/NuRD (MTA1) complexes could be recruited by transcription factors including Snail and ZEB2 and occupy the E-cadherin and AXIN2 promoters to induce tumorigenesis and breast cancer cell invasion." (PMID 34360879, 2021). "In breast cancer cells, FOSL1 expression correlates with mesenchymal features and drives cancer stem cells and the regulation of EMT seems to happen through the direct binding of FRA-1 to promoters of EMT genes such as Tgfb1, Zeb1, and Zeb2." (PMID 34399888, 2021). "The interaction between the Zeb2 NAT and Zeb2 pre-mRNA promotes the inclusion of the 5’UTR intron, thus increasing the levels of the Zeb2 protein, which can activate EMT (epithelial–mesenchymal transition) in breast cancer cells." (PMID 33407694, 2021). "For example, in breast cancer, the GATA3/G9A/NuRD(MTA3) complex inhibited the expression of Zeb2 by catalyzing H3K9 methylation of ZEB2 promoter, while Snail suppressed the expression of E-cadherin by recruiting histone lysine-specific demethylase 1 (LSD1) to CDH1 promoter." (PMID 33996581, 2021). "Mutual exclusivity data from the n = 1,105 breast cancer TCGA dataset revealed that PAPP-A has a significant tendency towards co-occurrence with mesenchymal markers Vimentin (VIM), SNAI1 (Snail), SNAI2 (Slug), Zeb1, Zeb2 and Twist1." (PMID 32792532, 2020). "A significant negative correlation between ZEB2 and miR-653 expression was observed in breast cancer tissues." (PMID 30979827, 2019). "In ZEB2-induced EMT, RAB25 down-regulation facilitates migration of cell lines from different origins, such as luminal-like (MCF7) or claudin-low (MDA-MB-231) breast cancer cells, and skin squamous carcinoma (A431) or colorectal cancer cells (HT29)." (PMID 30445998, 2018). "Therefore, by defining a mechanism for the regulation of ZEB2 independently of ZEB1, which is mediated by FOXP3 and miR-155, we have been able to analyse the specific contribution of ZEB2 in human breast cancer cells." (PMID 29963231, 2018).
breast carcinoma (continued). "One previous study found that S100A16 could promote EMT in breast cancer cells by elevating the expression of transcription factors Notch1, ZEB1, and ZEB2." (PMID 29746588, 2018). "Similarly, Foxf2 is essential for the proper downregulation of E-cadherin and the regulation of Zeb2 and Id2 during a TGFβ-induced EMT of Py2T murine breast cancer cells that have been derived from a tumor of the MMTV-PyMT mouse model of breast cancer." (PMID 30285803, 2018). "Therefore, ZEB1 and ZEB2 have essentially similar functions in the regulation of inflammatory response gene expression, especially IL6 and IL8, in the basal‐type breast cancer cells." (PMID 28618162, 2017). "Moreover, TWIST1, FOXC2, SNAIL1, ZEB2, and TWIST2 are overexpressed in stem-like cells isolated from primary breast carcinomas compared with more differentiated cancer cells." (PMID 28974015, 2017). "Perhaps consistent with this, breast cancers expressing higher levels of the epithelium-promoting miR-200 family that represses the CDH1-suppressing EMP drivers ZEB1 and ZEB2 have poorer outcomes; however, this appeared to be due to mechanisms additional to E-cadherin regulation." (PMID 28750639, 2017). "The down-regulation of ZEB1 and ZEB2 increased E-cadherin expression; in contrast, loss of miR-200, which occurs in many different human cancers, including breast cancer, ovarian cancer, prostate cancer, and endometrial carcinoma, results in increased ZEB1/ZEB2 and repression of E-cadherin." (PMID 25367080, 2014). "The breast cancer basal-like subtype-specific miRNAs, miR-221 and miR-222, promote EMT in breast cancer by targeting TRPS1 (trichorhinophalangeal syndrome type 1) which inhibits EMT by repressing ZEB2 expression." (PMID 22382486, 2012). "For instance, UBD shows elevated expression levels in breast cancer, and its down-regulation has been found to inhibit epithelial–mesenchymal transition (EMT) and the metastatic behavior of breast cancer cells, possibly through the stabilization of the ZEB2 protein." (PMID 41583390, 2026). "In breast cancer cells, the involvement of NF-κB extends to mediating the expression of key EMT transcription factors, including Slug, Sip1, and Twist1,alongside NF-κB-dependent regulation of ZEB-1/ZFHX1A and ZEB-2/ZFHX1B, also known as Smad-interacting protein." (PMID 39493763, 2024). "Together, this data indicates that CDH1, ZEB1, and ZEB2 genes do not represent direct transcriptional targets of GRHL2 in luminal breast cancer and their regulation may occur through post-transcriptional regulation in this cellular context." (PMID 36691073, 2023). "Another study indicated that in natural tamoxifen-resistant breast cancer cells (MDA-MB-231), the downregulation of linc-ROR could inhibit EMT and enhance sensibility to tamoxifen by increasing miR-205 expression and suppressing ZEB1 and ZEB2." (PMID 36827545, 2023). "As a regulator of epithelial-mesenchymal transition, ZEB2 is strongly downregulated by miR-221, and ZEB2 expression was increased, which in turn inhibited the expression of G9A and MTA3 by recruiting G9A/NuRD (MTA1), thereby promoting the metastasis and progression of breast cancer." (PMID 36072677, 2022). "Thus, ZEB2 and FAT10 are potential targets to prevent metastasis in the treatment of breast cancer." (PMID 34571823, 2021). "Deregulation of negative feedback between GATA3 and ZEB2 can promote breast cancer metastasis." (PMID 34368227, 2021). "Increased lnc-ROR was detected in breast cancer tissues and overexpressed lnc-ROR promoted epithelial–mesenchymal transition (EMT) and tamoxifen resistance by acting as a molecular sponge for miR-205 and increasing the expression of ZEB1 and ZEB2, given the binding sites between miR-205 and ZEB2." (PMID 33193591, 2020).
breast carcinoma (continued). "Since PC4 silencing could increase the migration and invasiveness in breast cancer cell lines, the expression pattern of different MMPs, mesenchymal markers like fibronectin, vimentin and regulators of EMT like, Zeb1 and Zeb2 was investigated upon silencing of PC4 in these cells." (PMID 31839879, 2019). "In conclusion, we speculate that ZEB2 and ZEB1 may have subtly different roles in breast cancer metastasis and that the current models of cancer progression may not reflect the complexity and hierarchy of the network of interactions that orchestrate these programmes." (PMID 29963231, 2018). "ZEB2 has a prominent role in driving epithelial to mesenchymal transition (EMT) in development, fibrosis and in cancer, where high levels correlate with many types of invasive cancer, including the most malignant form of breast cancer; the triple negative basal- like carcinoma." (PMID 29963231, 2018). "The purported tumor suppressive functions of miR-205 in breast cancer is due to direct targeting of several oncogenes such as VEGFA, E2F1, E2F5, PKC epsilon and HER3 reviewed in 16 as well as attenuating epithelial to mesenchymal transition (EMT) by suppressing ZEB1 and ZEB2." (PMID 24098490, 2013). "Data illustrating that high levels of ZEB2 are expressed in migratory breast cancer cell lines (MDA-MB-231 and MDA-MB-435S1) but not in breast cancer cells with a more epithelial/less migratory phenotype (MCF7/AZ) supports our finding that ZEB2 repression hampers the cellular migration." (PMID 21303533, 2011). "Furthermore, a large set of microRNAs co-regulates expression of both Zeb1 and Zeb2, modulating therefore tumor progression, for example miR-101 in ovarian carcinoma, miR-200 in gastric adenocarcinoma, miR-139 in HCC, miR-205 and miR-448 in breast cancer, and miR-590 in glioblastoma." (PMID 29843425, 2018). "Inhibition of the miR-200b-200a-429 promoter by ZEB2 was rescued by TBX1 in a dose-dependent manner in these cells, but not in MCF7 breast cancer cells." (PMID 36418889, 2022). "Among other findings, one of identified strongly connected components in the breast cancer interaction network contained the double-negative feedback loop between miRNAs from mir-200 family and ZEB1/ZEB2 genes." (PMID 33852600, 2021). "Taken together, these results indicated that in addition to vimentin, MTHFD2 depletion reduced N-cadherin expression but did not significantly modulate ZEB1, ZEB2 and SLUG transcription in MDA-MB-231(SA) breast cancer cells." (PMID 23295955, 2013). "In spite of the fact that in human breast cancer cells, NF-κB binds to the promoter regions of Snai2, Twist1, and ZEB2 and activates their transcription, PDGF-AB does not increase the expression of Snai2, Twist1, and ZEB2 in brain ECs." (PMID 32226439, 2020). "Thus, we propose that FOXP3 and miR-155 co-operate to down regulate ZEB2, but not ZEB1, in breast cancer cells." (PMID 29963231, 2018).
melanoma (69 papers, 2014 to 2026). A malignant, usually aggressive tumor composed of atypical, neoplastic melanocytes. "In the 6-week-old infant with melanoma and a second case occurring at 10 months, a ZEB2:ALK fusion were found in associated benign tumors, up to 10 months before malignancy was detected." (PMID 39755235, 2025). "In clinical research, reduced ZEB2 levels correlated with lower survival rates in melanoma patients, whereas elevated ZEB1 expression was linked to poorer clinical prognoses." (PMID 40356596, 2025). "In clinical studies, ZEB2 deficiency was associated with reduced survival in melanoma patients, while ZEB1 expression was associated with poorer clinical outcomes." (PMID 36076302, 2022). "It was reported that ZEB1 expression is associated with an invasive phenotype while ZEB2 expression is required for the proliferative melanoma cell state." (PMID 36232952, 2022). "ZEB2 is associated with metastasis in ovarian, gastric and pancreatic tumors but reduces aggressiveness in melanoma." (PMID 34948036, 2021). "Strong ZEB2/SLUG expression in melanoma is associated with high levels of MITF and downstream melanocyte differentiation markers." (PMID 32796736, 2020). "A high ZEB2/SLUG expression signature is associated with a more differentiated melanoma state and better patient prognosis." (PMID 32796736, 2020). "As such, it is to be expected that some of these micro-environmental associated signalling pathways regulate melanoma plasticity through modulation of the balance between ZEB2 and ZEB1." (PMID 32796736, 2020). "ZEB2, another core EM-TF from the ZEB family, displayed opposite effects in mouse melanomas; ZEB2 decreased the malignant progression and the loss of ZEB2 increased it." (PMID 32998363, 2020). "Accordingly, the switch from ZEB2 to ZEB1 in the NRAS melanoma mouse model is associated with the gain of an invasive phenotype." (PMID 32759677, 2020). "It was also shown that Zeb2 is involved in acquired resistance to the BRAF inhibitor in BRAF-mutated melanoma." (PMID 31231466, 2019). "The study also demonstrated that loss of ZEB2 in melanocytes resulted in dedifferentiation, and in melanoma cells resulted in increased ZEB1expression, repressing E-Cadherin, and contributing to progression and metastasis." (PMID 25763355, 2015). "Indeed, the loss of SNAI2/ZEB2 combined with the gain of ZEB1 is a factor involved in the poor prognosis of melanoma patients and is associated with resistance to MAPK-targeting and immune therapies." (PMID 38398085, 2024). "Furthermore, a recent study shows that ZEB2 is not only associated with but actually acts as an essential driver of melanoma development and growth in vivo." (PMID 32796736, 2020). "Loss of ZEB2 expression was already reported to be associated with poor melanoma-specific survival." (PMID 31745173, 2019). "PTEN is also deregulated in melanoma via loss of ZEB2, a competitive endogenous RNA (ceRNA)." (PMID 24743024, 2014). "For example, in a melanoma mouse model, ZEB2 inhibits cancer metastasis, whereas ZEB1 promotes tumor initiation and progression." (PMID 40356596, 2025). "ZEB2 (zinc finger E−box-binding homeobox 2) is often highly expressed in melanomas and is a 5′ fusion partner in other chimeric oncogenes in a variety of cancers." (PMID 39755235, 2025). "When B16-F10 melanoma cells were co-cultured with T lymphocytes in hypoxic conditions, ZEB2 expression was inhibited with suppressed cytotoxic activity of T-cells showing a resistance strategy for immune escape." (PMID 38426087, 2024). "The DepMap survey also found significant direct relationships between SNAI1 and ZEB1 as well as SNAI2 and ZEB2 in melanoma cell lines, further supporting a potential role for snail and ZEB transcription factors in the CoREST-mediated phenotype switch." (PMID 38300709, 2024). "ZEB2 is expressed in normal melanocytes and its expression progressively decreases during transformation to melanoma, while ZEB1 expression increases." (PMID 38519642, 2024).